TRAPPC2L (trafficking protein particle complex subunit 2L)
Description:
Plays a role in vesicular transport from endoplasmic reticulum to Golgi.
Synonyms: HSPC176; PERRB
Tractability: PROTAC: ubiquitination databases record sites on it; its protein half-life has been measured.
Gene: Protein-coding gene on chromosome 16 (88,856,220 to 88,862,686, forward strand). Ensembl gene ENSG00000167515.
Subcellular location: Cytoplasm, perinuclear region; Endoplasmic reticulum; Golgi apparatus
Subcellular location (Human Protein Atlas): Cytosol; Vesicles
Pathways (Reactome):
Vesicle-mediated transport: COPII-mediated vesicle transport; RAB GEFs exchange GTP for GDP on RABs
Gene Ontology:
Molecular function: protein binding
Biological process: COPII vesicle coating; endoplasmic reticulum to Golgi vesicle-mediated transport; vesicle coating
Cellular component: cytosol; TRAPP complex; cytoplasm; nucleus; TRAPPII protein complex; TRAPPIII protein complex; endoplasmic reticulum; Golgi apparatus; perinuclear region of cytoplasm
Genetic constraint (gnomAD): Loss-of-function variants: 17 observed, 12.02 expected, observed/expected ratio (o/e) 1.41, 90% interval 0.96 to 1.9. The upper end of that interval is the gene's LOEUF score, 1.9, which puts it in group 6 of 6, group 1 being the genes least tolerant of losing a copy. Missense variants: 227 observed, 181.03 expected, observed/expected ratio (o/e) 1.25, 90% interval 1.12 to 1.4. Synonymous variants: 94 observed, 73.01 expected, observed/expected ratio (o/e) 1.29, 90% interval 1.09 to 1.53.
Homologues: Orthologues: mouse Trappc2l (99% identical), guinea pig TRAPPC2L (98% identical), dog TRAPPC2L (97% identical), rat LOC100909916 (96% identical), macaque TRAPPC2L (94% identical), tropical clawed frog trappc2l (92% identical), pig TRAPPC2L (88% identical), zebrafish trappc2l (86% identical), Drosophila melanogaster CG9067 (53% identical), Caenorhabditis elegans T10F2.5 (32% identical). Paralogues in human: TRAPPC2 (26% identical), TRAPPC2B (26% identical).
Diseases named in the same sentence as TRAPPC2L in open-access papers:
TRAPPC2L is named in the same sentence as 10 diseases in open-access papers, as found by Europe PMC text mining. Sharing a sentence is not in itself a finding about the gene and the disease. The quoted sentences say what the papers report.
Neurodevelopmental delay (2 papers, 2022 to 2025). "It has been reported that a homozygous missense mutation in TRAPPC2L gene was detected in two unrelated patients with neurodevelopmental delay and epilepsy." (PMID 40539230, 2025). "Mutations in Trappc2l gene are associated with neurodevelopmental disorders, characterised by severe neurodevelopmental delays and varying degrees of muscle abnormalities." (PMID 40539230, 2025).
gastric cancer (1 paper, 2010). A primary or metastatic malignant neoplasm involving the stomach. "The TRAPPC2L, DUSP6, MLH1 and RUNX3 genes more than 3-kb distal from the nearest retroelements were similarly overmethylated in the H. pylori positive mucosa (43%) and gastric cancers (LOH-B, 44%; LOH-L, 47%; LOH-H, 33%)." (PMID 21092120, 2010).
infertile (1 paper, 2020). "Similarly, miR-10b, previously associated with human infertile semen samples, correlated with a motility-related parameter (VCL) and interacted with 32 genes (including the previously discussed TRAPPC2L that is present in the final network)." (PMID 33292187, 2020).
male infertility (1 paper, 2025). The inability of the male to effect fertilization of an ovum after a specified period of unprotected intercourse. "Inactivation of Trappc2l caused male germ cells abnormal cell division and formed syncytial structures which in turn led to germ cell loss and male infertility." (PMID 40539230, 2025).
microcephaly (1 paper, 2022). A congenital or acquired developmental disorder in which the circumference of the head is smaller than normal for the person's age and sex. "Five direct known interactions were found between HLHS candidates and microcephaly-associated genes (HLHS candidates are shown in bold): TSC1-POGZ, TSC1-CDK6, CTNNBL1-STAMBP, TRAPPC2L-TRAPPC6B and TSC22D1-QARS1." (PMID 35456433, 2022).
Obesity (1 paper, 2024). Accumulation of substantial excess body fat. "However, patients bearing mutations of Trappc2, Trappc2l, Trappc4, Trappc6A/B, or Trappc10 do not develop obesity as patients with Trappc9 mutations do." (PMID 38889014, 2024).
neurodevelopmental disorder (2 papers, 2022 to 2025). A behavioral and cognitive disorder with onset during the developmental period that involves impaired or aberrant development of intellectual, motor, or social functions. "S6) in a manner identical to that recently predicted computationally, at the site of a mutation in the human Tca17 paralog TRAPPC2L that disrupts this interaction and is associated with a neurodevelopmental disorder." (PMID 35559680, 2022). "Mutations in TRAPPC2L disrupt RAB11 activity, impairing membrane transport and maintenance, ultimately leading to neurodevelopmental disorders characterised by severe neurodevelopmental delays and varying degrees of muscle abnormalities." (PMID 40539230, 2025).
TRAPPC2L also shares sentences with these, for which no sentence is quoted: infection (2 papers); epilepsy (1); intellectual disabilities (1).